LMCD1 (LIM and cysteine rich domains 1)
Description:
Transcriptional cofactor that restricts GATA6 function by inhibiting DNA-binding, resulting in repression of GATA6 transcriptional activation of downstream target genes. Represses GATA6-mediated trans activation of lung- and cardiac tissue-specific promoters. Inhibits DNA-binding by GATA4 and GATA1 to the cTNC promoter (By similarity). Plays a critical role in the development of cardiac hypertrophy via activation of calcineurin/nuclear factor of activated T-cells signaling pathway.
Tractability: No criterion of Open Targets' tractability assessment is met for any kind of drug.
Gene: Protein-coding gene on chromosome 3 (8,501,587 to 8,574,668, forward strand). Ensembl gene ENSG00000071282.
Subcellular location: Cytoplasm; Nucleus
Subcellular location (Human Protein Atlas): Nucleoplasm; Plasma membrane; Cell Junctions; Cytosol
Pathways (Reactome):
Metabolism of proteins: Surfactant metabolism
Gene Ontology:
Molecular function: protein binding; transcription corepressor activity; zinc ion binding
Biological process: positive regulation of calcineurin-NFAT signaling cascade; regulation of cardiac muscle hypertrophy; negative regulation of DNA-templated transcription
Cellular component: nucleoplasm; nucleus; cytoplasm
Genetic constraint (gnomAD): Loss-of-function variants: 32 observed, 44.24 expected, observed/expected ratio (o/e) 0.72, 90% interval 0.55 to 0.97. The upper end of that interval is the gene's LOEUF score, 0.97, which puts it in group 4 of 6, group 1 being the genes least tolerant of losing a copy. Missense variants: 458 observed, 502.43 expected, observed/expected ratio (o/e) 0.91, 90% interval 0.84 to 0.99. Synonymous variants: 178 observed, 193.87 expected, observed/expected ratio (o/e) 0.92, 90% interval 0.81 to 1.04.
Homologues: Orthologues: chimpanzee LMCD1 (99% identical), macaque LMCD1 (99% identical), pig LMCD1 (93% identical), guinea pig LMCD1 (93% identical), rat Lmcd1 (93% identical), mouse Lmcd1 (93% identical), rabbit LMCD1 (90% identical), dog LMCD1 (87% identical), tropical clawed frog lmcd1 (56% identical), zebrafish lmcd1 (52% identical), Drosophila melanogaster Tes (30% identical), Caenorhabditis elegans tes-1 (24% identical), and 1 more. Paralogues in human: TES (49% identical), PRICKLE1 (27% identical), LIMD2 (7% identical).
Diseases named in the same sentence as LMCD1 in open-access papers:
LMCD1 is named in the same sentence as 27 diseases in open-access papers, as found by Europe PMC text mining. Sharing a sentence is not in itself a finding about the gene and the disease. The quoted sentences say what the papers report.
cardiac hypertrophy (7 papers, 2011 to 2025). "LMCD1 has been shown to induce cardiac hypertrophy and mutations in the LMCD1 gene have been involved in the regulation of hepatocellular carcinoma cell migration." (PMID 31666122, 2019). "Functionally, LMCD1 regulates cardiac hypertrophy and thrombin‐induced smooth muscle cell proliferation by interacting with different transcription factors." (PMID 32840323, 2020). "A recent study has shown that LMCD1 regulates cardiac hypertrophy by targeting calcium‐related NFAT signaling." (PMID 32840323, 2020). "Previous studies have confirmed the function of LMCD1 in cardiac hypertrophy, thrombin formation, and hepatocellular carcinoma migration." (PMID 31501411, 2019). "LMCD1 encodes for a poorly characterized cysteine-rich and LIM domain-containing protein, which has been so far implicated in cardiac hypertrophy." (PMID 21646684, 2011).
hepatocellular carcinoma (3 papers, 2016 to 2019). A malignant tumor that arises from hepatocytes. "LMCD1 E135K somatic mutation was associated with cell migration and tumor metastasis in hepatocellular carcinoma (HCC); its up‐regulation was also positively correlated with infiltrative tumor growth patterns in HCC patients, implying its possible involvement in tumor cell invasiveness." (PMID 27318801, 2016).
renal fibrosis (2 papers, 2024 to 2025). A final common manifestation of a wide variety of chronic kidney diseases characterized by glomerulosclerosis and tubulointerstitial fibrosis. "LMCD1 is upregulated in the kidney tissues of patients with chronic kidney disease, and its silencing ameliorates renal fibrosis in mice." (PMID 40650665, 2025). "Notably, a previous study showed that LMCD1 upregulation promotes unilateral ureteral obstruction‐induced kidney injury by facilitating renal fibrosis and RTEC apoptosis." (PMID 40650665, 2025). "As previously reported, LMCD1 upregulation promotes renal fibrosis in mice." (PMID 40650665, 2025). "Evidence suggests that LMCD1 may facilitate profibrotic gene expression, and in tissue fibrosis, it is found to be consistently elevated in pulmonary and renal fibrosis." (PMID 38994947, 2024).
alopecia (1 paper, 2019). Hair loss usually from the scalp. "The differential expression of LIM and cysteine-rich domains 1 (LMCD1) causes the aberration of Notch and Hedgehog signaling pathways leading to alopecia and hair-loss." (PMID 30993080, 2019). "The differential expression of WIF1, PTPRE, HBB, and LMCD1 is associated with hair loss, morphogenesis, and alopecia." (PMID 30993080, 2019).
asthenospermia (1 paper, 2020). "Using a previously validated in vivo siRNA approach, we showed that LMCD1 depletion significantly impaired male fertility by inducing oligozoospermia and asthenospermia." (PMID 32840323, 2020). "In accordance with these morphological changes, Lmcd1 knockdown significantly impaired fertility potential by inducing oligozoospermia and asthenospermia." (PMID 32840323, 2020).
cryptorchidism (1 paper, 2025). The failure of one or both testes of a male fetus to descend from the abdomen into the scrotum during the late part of pregnancy. "The results showed that six target proteins of TJP2, ZO-1, SYNPO2, SYNPO, LMCD1, and MCU showed characteristic distribution in the epididymal tissues of the cryptorchidism group and the normal control group." (PMID 41217791, 2025).
Duchenne muscular dystrophy (1 paper, 2019). Duchenne muscular dystrophy (DMD) is a neuromuscular disease characterized by rapidly progressive muscle weakness and wasting due to degeneration of skeletal, smooth and cardiac muscle. "From this analysis, we identified Lmcd1, which showed significantly decreased expression in diseases such as Duchenne muscular dystrophy and myotonic dystrophy." (PMID 31666122, 2019). "Here, we show that LMCD1 is reduced in skeletal muscle of patients with diseases such as Duchenne muscular dystrophy and myotonic dystrophy." (PMID 31666122, 2019).
Emery-Dreifuss muscular dystrophy (1 paper, 2023). Emery-Dreifuss muscular dystrophy (EDMD) is characterized by muscular weakness and atrophy, with early joint contractures and cardiomyopathy. "CSRP3, LMCD1, ALDOA, PERM1: candidate genes for Emery-Dreifuss muscular dystrophy that may also provide insight into frailty-related muscle weakness?" (PMID 37936983, 2023).
endothelial dysfunction (1 paper, 2025). In vascular diseases, endothelial dysfunction is a systemic pathological state of the endothelium (the inner lining of blood vessels) and can be broadly defined as an imbalance between vasodilating and vasoconstricting substances produced by (or acting on) the endothelium. "LMCD1 mediates IL-33 expression, which plays a role in endothelial dysfunction." (PMID 39967738, 2025).
lung fibrosis (1 paper, 2024). "In particular, in cases of systemic sclerosis-associated lung fibrosis, LMCD1 interacts with serum response factors in lung fibroblasts, which leads to increased contractile activity of lung myofibroblasts." (PMID 38660492, 2024). "It has been shown that LMCD1 plays an important role in the development of lung fibrosis and affects the properties of lung myofibroblasts." (PMID 38660492, 2024). "Lung fibrosis and lung myofibroblasts also play important roles in the pathophysiology of COPD, and it is reasonable to hypothesize that LMCD1 could potentially contribute to lung tissue fibrosis, thereby increasing the risk of spirometry-defined COPD." (PMID 38660492, 2024).
male infertility (1 paper, 2020). The inability of the male to effect fertilization of an ovum after a specified period of unprotected intercourse. "To note, unlike other key factors regulating phagocytosis in SCs, mice treated with Lmcd1 Stealth siRNAs in vivo only displayed impaired male infertility but not absolute sterility." (PMID 32840323, 2020).
sarcopenia (1 paper, 2023). Progressive decline in muscle mass due to aging which results in decreased functional capacity of muscles. "Its reduced association with lamin A/C in IL10-KO muscle suggests Lmcd1 is also relevant to sarcopenia and fatigue in frailty and warrants further testing." (PMID 37936983, 2023).
Sepsis (1 paper, 2025). Sepsis is defined as life-threatening organ dysfunction caused by a dysregulated host response to infection. "LPS is commonly used as an inducer in SA‐AKI cell models, and our findings suggest that LMCD1 is a potential biomarker for sepsis and a target for ferroptosis therapy." (PMID 40650665, 2025).
steatosis (1 paper, 2024). Increased lipid within the cytoplasm of cells. "Therefore, we selected the RPS6KA1 and LMCD1 genes as diagnostic for steatosis and AS, and the RPS6KA1 SYNP02, JAML and SERPINA3 genes as diagnostic for NASH and AS." (PMID 38606153, 2024). "We found that RPS6KA1 expression differed between the steatosis and NASH groups, with all AUCs being > 0.7, whereas LMCD1 expression differed only in the steatosis group." (PMID 38606153, 2024).
tumor (5 papers, 2016 to 2024). "Expression levels of other activin A target genes, including Adam12, Pmepa1, and Lmcd1—known to be involved in receptor endocytosis, fibrogenesis, and tumor progression —were significantly elevated by activin A (confirming our previous studies), and entirely antagonized by NUCC-555." (PMID 38607090, 2024). "Our data directly reveal for the first time to our knowledge that upregulated LMCD1 may intermediate EMT progression and contribute to tumor cell invasiveness and metastasis." (PMID 27318801, 2016). "However, TOX, LMCD1, and AFAP1L2 were either not detected or only at very low levels, suggesting that their presence in tumor-infiltrating T cells was not a consequence of the canonical T cell activation program." (PMID 37388918, 2023).
cancer (3 papers, 2020 to 2021). A tumor composed of atypical neoplastic, often pleomorphic cells that invade other tissues. "LIM and cysteine-rich domains 1 (LMCD1) had been found acting as an activator E2F1 transcription factor in human cells but its role in cancers were rarely investigated." (PMID 33682883, 2021).
cardiovascular diseases (1 paper, 2025). "The elevated expression of LMCD1 enhanced the cell proliferation and migration in VSMCs in vitro experiments, suggesting that LMCD1 may be an important factor in vascular remodeling and the pathogenesis of severe cardiovascular diseases." (PMID 40362300, 2025).
LMCD1 also shares sentences with these, for which no sentence is quoted: breast carcinoma (1 paper); cervical cancer (1); infection (1); myotonic dystrophy (1); oral cancer (1); prostate carcinoma (1); prostate tumors (1); sterility (1); systemic sclerosis (1); Ureteral obstruction (1).